CHASERR (CHD2 adjacent suppressive regulatory RNA)
Synonyms: formerly LINC01578
Gene: Long non-coding RNA gene on chromosome 15 (92,819,305 to 92,899,701, forward strand). Ensembl gene ENSG00000272888.
Diseases named in the same sentence as CHASERR in open-access papers:
CHASERR is named in the same sentence as 9 diseases in open-access papers, as found by Europe PMC text mining. Sharing a sentence is not in itself a finding about the gene and the disease. The quoted sentences say what the papers report.
glioma (2 papers, 2024 to 2025). A benign or malignant brain and spinal cord tumor that arises from glial cells (astrocytes, oligodendrocytes, ependymal cells). "For instance, a study showed that lncRNA CHASERR is significantly upregulated in glioma tissues and indicates a poor prognosis in glioma patients." (PMID 38967893, 2024).
autoimmune uveitis (1 paper, 2025). An autoimmune form of uveitis (disease). "In both our CHASERR knockdown model and in cyclosporine-treated autoimmune uveitis mice, we observed a consistent decrease in CHD2 levels without a corresponding increase in CHASERR expression." (PMID 41306969, 2025).
neurological disorder (2 papers, 2025). "Recently, CHASERR itself was shown to be critical for viability, and its deletion was associated with a neurological disorder." (PMID 38076842, 2025).
CHASERR also shares sentences with these, for which no sentence is quoted: colon cancer (2 papers); breast carcinoma (1); cancer (1); colorectal cancer (1); lymph node metastasis (1); tumor (1).